UCK1 (uridine-cytidine kinase 1)
Description:
Phosphorylates uridine and cytidine to uridine monophosphate and cytidine monophosphate. Does not phosphorylate deoxyribonucleosides or purine ribonucleosides. Can use ATP or GTP as a phosphate donor. Can also phosphorylate cytidine and uridine nucleoside analogs such as 6-azauridine, 5-fluorouridine, 4-thiouridine, 5-bromouridine, N(4)- acetylcytidine, N(4)-benzoylcytidine, 5-fluorocytidine, 2-thiocytidine, 5-methylcytidine, and N(4)-anisoylcytidine.
Synonyms: URK1; FLJ12255
Tractability: Small molecule: a structure with a bound ligand is known; a high-quality ligand is known; it has a high-quality binding pocket. PROTAC: ubiquitination databases record sites on it.
Target class: Enzyme; Transferase
Gene: Protein-coding gene on chromosome 9 (131,523,786 to 131,531,280, reverse strand). Ensembl gene ENSG00000130717.
Subcellular location (Human Protein Atlas): Nucleoplasm; Nucleoli
Pathways (Reactome):
Metabolism: Pyrimidine salvage
Gene Ontology:
Molecular function: cytidine kinase activity; uridine kinase activity; ATP binding; kinase activity
Biological process: CTP salvage; UMP salvage; CMP biosynthetic process
Cellular component: cytosol
Genetic constraint (gnomAD): Loss-of-function variants: 19 observed, 30.1 expected, observed/expected ratio (o/e) 0.63, 90% interval 0.44 to 0.93. The upper end of that interval is the gene's LOEUF score, 0.93, which puts it in group 3 of 6, group 1 being the genes least tolerant of losing a copy. Missense variants: 334 observed, 364.38 expected, observed/expected ratio (o/e) 0.92, 90% interval 0.84 to 1. Synonymous variants: 166 observed, 151.71 expected, observed/expected ratio (o/e) 1.09, 90% interval 0.96 to 1.25.
Homologues: Orthologues: chimpanzee UCK1 (100% identical), macaque UCK1 (99% identical), dog UCK1 (95% identical), pig UCK1 (94% identical), rat Uck1 (92% identical), mouse Uck1 (92% identical), tropical clawed frog uck1 (82% identical), zebrafish uck1 (77% identical), guinea pig UCK1 (65% identical), Drosophila melanogaster Uck (56% identical), Caenorhabditis elegans B0001.4 (42% identical). Paralogues in human: UCK2 (68% identical), UCKL1 (44% identical), UPRT (9% identical).
Diseases named in the same sentence as UCK1 in open-access papers:
UCK1 is named in the same sentence as 10 diseases in open-access papers, as found by Europe PMC text mining. Sharing a sentence is not in itself a finding about the gene and the disease. The quoted sentences say what the papers report.
leukemia (3 papers, 2017 to 2020). A malignant (clonal) hematologic disorder, involving hematopoietic stem cells and characterized by the presence of primitive or atypical myeloid or lymphoid cells in the bone marrow and the blood. "Moreover, UCK1, SLC25A38, VDAC1 in our signature have been reported to be involved in proliferation or apoptosis of leukemia cell lines." (PMID 27903973, 2017). "Therefore, we performed additional in vitro experiments based on the two best 5-protein models (which shared TYMP, RRM1, UPP1, and UCK1 and contained either PPAT or UCK2) using two CRC and two leukemia cell lines that are predicted to be sensitive or resistant to 5FU." (PMID 32686665, 2020).
colon cancer (1 paper, 2018).
endometrial carcinoma (1 paper, 2020). A malignant tumor arising from the epithelium that lines the cavity of the uterine body. "TYMP had the highest percentage of mutation, especially in ovarian epithelial cancer, while UCK1, which is frequently mutated in endometrial carcinoma, is the less present among the screened genes." (PMID 32887417, 2020).
fibrosarcoma (1 paper, 2020). A malignant mesenchymal fibroblastic neoplasm affecting the soft tissue and bone. "Indeed, UCK1 is not often observed mutated and, as already evaluated by Murata and colleagues, its level did not change even in a chemoresistant model of human fibrosarcoma and gastric carcinoma." (PMID 32887417, 2020).
myelodysplastic syndrome (1 paper, 2016). A clonal hematopoietic disorder characterized by dysplasia and ineffective hematopoiesis in one or more of the hematopoietic cell lines. "A lower UCK1 expression for myelodysplastic syndrome (MDS) patients has been associated with reduced survival rate, while point mutations in UCK2 have been found in human leukemic cell lines made resistant to Aza-CR." (PMID 27612203, 2016).
cancer (4 papers, 2014 to 2025). A tumor composed of atypical neoplastic, often pleomorphic cells that invade other tissues. "UCK1 is present in both cancer and normal cells, whereas UCK2 is preferentially expressed in various cancer cells, including neuroblastoma cells." (PMID 40804482, 2025). "In particular, UCK2 is preferentially expressed in cancer cells, while UCK1 expression is observed in both cancer and normal cells, explaining the greater anti-tumor effect on cancer cells while sparing normal cells." (PMID 25087851, 2014). "UCK1 is expressed universally in various tissues, while UCK2 is known to be expressed only in human placenta and several types of cancers." (PMID 37297025, 2023). "However, in a panel of 60 cancer cell lines, AZA sensitivity correlated with UCK2 but not UCK1 expression." (PMID 36834962, 2023).
tumor (2 papers, 2016 to 2022). "UCK1 and UCK2 show a sequence similarity of 72%, and UCK2 has a higher catalytic efficiency than UCK1, indicating that UCK2 is an ideal target for tumour treatment." (PMID 36447138, 2022). "UCK1 is ubiquitously expressed in several tissues, whereas UCK2 is expressed in the human placenta and tumour tissues." (PMID 36447138, 2022). "UCK enzyme activity in two panels of tumor cell lines and xenograft cells correlated only with UCK2-mRNA expression (r = 0.803 and 0.915, respectively), but not with UCK1-mRNA." (PMID 27612203, 2016).
UCK1 also shares sentences with these, for which no sentence is quoted: gastric carcinoma (1 paper); lung carcinoma (1); ovarian epithelial cancer (1).